PTH (parathyroid hormone)
Diseases named in the same sentence as PTH in open-access papers (continued):
Sharing a sentence is not in itself a finding about the gene and the disease.
pseudohypoparathyroidism (continued). "Due to the increase in PTH levels and the clinical phenotype, pseudohypoparathyroidism was suspected and the patient was referred for genetic assessment." (PMID 39456695, 2024). "Pseudohypoparathyroidism (PHP) belongs to a group of metabolic disorders called “inactivating parathyroid hormone (PTH)/parathyroid hormone-related protein PTHrp) signaling disorders (iPPDs)”." (PMID 39267114, 2024). "Pseudohypoparathyroidism is a rare metabolic disorder marked by resistance to parathyroid hormone (PTH)." (PMID 39350885, 2024). "The laboratory biochemical analysis revealed that the proband’s calcium level was 1.63 mmol/L, her potassium level was 2.91 mmol/L, and her parathyroid hormone level was 412.7 ng/L, indicating a diagnosis of pseudohypoparathyroidism." (PMID 39519162, 2024). "Due to the increase in PTH levels, the occurrence of new subcutaneous, calcific lesions, and the clinical phenotype, pseudohypoparathyroidism, was suspected and the patient was referred for a genetic assessment." (PMID 39456695, 2024). "Previous studies have suggested that these metabolic disruptions, commonly seen in pseudohypoparathyroidism and other parathyroid hormone (PTH)-related conditions, can adversely affect the formation and eruption of teeth." (PMID 39519162, 2024). "Inactivating Gsα mutations lead to multihormone resistance, including end-organ resistance to the parathyroid hormone (PTH), termed pseudohypoparathyroidism (PHP)." (PMID 36853809, 2023). "Pseudohypoparathyroidism (PHP) encompasses a highly heterogenous group of disorders, characterized by parathyroid hormone (PTH) resistance caused by mutations in the GNAS gene or other upstream targets." (PMID 35410271, 2022). "The term Pseudohypoparathyroidism-PHP encompasses a group of heterogeneous disorders caused by different genetic and/or epigenetic defects affecting the PTH/PTHrP signaling pathway." (PMID 33179219, 2021). "Pseudohypoparathyroidism (PHP) comprises a heterogeneous group of rare related disorders characterised by diminished activation of the Gsα/cAMP/PKA signalling pathway by the parathyroid hormone (PTH) and other hormones (for review:)." (PMID 33920525, 2021). "Pseudohypoparathyroidism comprehends an assorted group of genetically rare disorders that share end-organ resistance to parathyroid hormone." (PMID 33320452, 2020). "Pseudohypoparathyroidism (PHP) is a heterogeneous group of disorders due to impaired activation of c AMP dependant pathways following binding of parathyroid hormone (PTH) to its receptor." (PMID 31856822, 2019). "Pseudohypoparathyroidism (PHP) is a rare endocrine disorder derived from the defective activation of the cAMP pathway by the parathyroid hormone secondary to GNAS molecular defects." (PMID 31555217, 2019). "The disorders related to parathyroid hormone (PTH) resistance and PTH signalling pathway impairment are historically named pseudohypoparathyroidism (PHP)." (PMID 30616679, 2019). "The term pseudohypoparathyroidism (PHP) describes disorders derived from resistance to the parathyroid hormone." (PMID 30616679, 2019). "Pseudohypoparathyroidism type 1A (PHP1A) is a rare genetic disease primarily characterized by resistance to parathyroid hormone along with hormonal resistance and other features of Albright hereditary osteodystrophy (AHO)." (PMID 30060753, 2018). "Pseudohypoparathyroidism is a rare condition that is due to a defect in the stimulatory G-protein coupled receptor, resulting in end-organ resistance to parathyroid hormone." (PMID 29387507, 2017). "Pseudohypoparathyroidism is one of the disorders associated with GNAS locus deficit, and the GNAS locus is associated with RPTC responses to parathyroid hormone and electrolyte balance." (PMID 28715443, 2017). "Disorders related to parathyroid hormone (PTH) resistance and PTH signaling pathway impairment are historically classified under the term of pseudohypoparathyroidism (PHP)." (PMID 29280743, 2017).
pseudohypoparathyroidism (continued). "Pseudohypoparathyroidism (PTH resistance of kidney and bone presenting with high PTH and low calcium) is a separate disorder that can be seen rarely." (PMID 28138323, 2016). "Pseudohypoparathyroidism (PHP) is a group of disorders united by parathyroid hormone (PTH) resistance in the kidney, that is, pseudohypoparathyroidism." (PMID 25784961, 2015). "PHP is a group of disorders characterised by PTH resistance in the kidney, i.e. pseudohypoparathyroidism." (PMID 26583054, 2015). "Biochemical analysis showed calcium values in the lower limit of normality (8.5–9.3mg/dl) and elevated PTH (200–300pg/ml), so she was diagnosed of pseudohypoparathyroidism." (PMID 25710380, 2015). "Maternally inherited inactivating GNAS mutations are the most common cause of parathyroid hormone (PTH) resistance and Albright hereditary osteodystrophy (AHO) leading to pseudohypoparathyroidism type Ia (PHPIa) due to Gsα deficiency." (PMID 25802881, 2015). "An Ellsworth-Howard test showed only a fivefold increase in urinary phosphate excretion after administration of synthetic PTH, supporting the diagnosis pseudohypoparathyroidism." (PMID 22937298, 2012). "Pseudohypoparathyroidism (PHP) is a rare disorder characterized by varying degrees of unresponsiveness to parathyroid hormone." (PMID 22394705, 2012). "Pseudohypoparathyroidism (PHP) is an inherited disorder characterized by end−organ resistance to parathormone (PTH)." (PMID 21274319, 2010). "Pseudohypoparathyroidism (PHP) refers to end−organ resistance that primarily impairs the renal actions of parathyroid hormone (PTH)." (PMID 21274345, 2010). "Pseudohypoparathyroidism (PHP) is an inherited disorder characterized by an end−organ resistance to parathormone (PTH)." (PMID 21274319, 2010). "Pseudohypoparathyroidism refers to a heterogeneous group of disorders characterized by parathyroid hormone (PTH) resistance." (PMID 19829854, 2009). "The elevated PTH levels found in patient 2 are compatible with the diagnosis of pseudohypoparathyroidism." (PMID 11836550, 2002). "Pseudohypoparathyroidism is a clinical entity arising out from peripheral resistance to PTH." (PMID 39351120, 2024). "Pseudohypoparathyroidism (PHP) is a group of rare endocrine disorders of calcium metabolism characterized by renal resistance to the parathyroid hormone (PTH) due to impaired intracytoplasmic receptor signaling caused by de novo or autosomal dominant (epi)genetic mutations of GNAS locus." (PMID 38137593, 2023). "Other rare causes of elevated PTH like pseudohypoparathyroidism should also be excluded, but none of our patients presented with very high PTH in the setting of hypocalcemia." (PMID 36187131, 2022). "Pseudohypoparathyroidism (PHP), the first known post-receptorial hormone resistance, derives from a partial deficiency of the α subunit of the stimulatory G protein (Gsα), a key component of the PTH/PTHrP signaling pathway." (PMID 33179219, 2021). "PTH resistance of pseudohypoparathyroidism may be transient as in the case of renal dysplasia or obstructive uropathy or permanent because of GNAS mutations." (PMID 31320908, 2019). "Pseudohypoparathyroidism (PHP) is a rare endocrine disorder derived from the defective activation of the cAMP transduction pathway by the parathyroid hormone (PTH) secondary to molecular defects affecting the alpha subunit of the stimulatory G protein (Gsα), which is encoded by the GNAS gene." (PMID 31555217, 2019). "Pseudohypoparathyroidism (PHP) is characterized by target organ resistance to PTH." (PMID 30540559, 2019). "Other molecular defects (for example, modification in GNAS methylation) or defects in other mediators of PTH signaling in target tissues (for example, PRKAR1A) may also cause pseudohypoparathyroidism (A)." (PMID 29694629, 2018). "Pseudohypoparathyroidism is divided into types I and II according to the absence or presence, respectively, of an increment in urinary cAMP excretion in response to exogenous PTH administration." (PMID 27415614, 2016).
pseudohypoparathyroidism (continued). "However, we note that POH is classified among the pseudohypoparathyroidism (PHP) disorders, caused by deficiencies in Gnas/Gsα and/or downstream signaling effectors, some of which are accompanied by resistance to PTH and/or other hormones and by altered serum biochemistries." (PMID 33574833, 2021). "Calcium and phosphate levels, along with parathyroid hormone (PTH) and calcitonin, were assessed in patients with suspected pseudohypoparathyroidism." (PMID 40149731, 2025). "The term pseudohypoparathyroidism (PHP) refers to a spectrum of genetic disorders characterized by clinical and biological features of resistance to parathyroid hormone (PTH)." (PMID 38664677, 2024). "Pseudohypoparathyroidism (PHP) is a rare disorder characterized by low levels of calcium, high levels of phosphorus, elevated PTH levels in the blood, and parathyroid hormone (PTH) resistance." (PMID 38397265, 2024). "Pseudohypoparathyroidism (PHP) is a rare, heterogeneous disorder characterized by end-organ resistance to parathyroid hormone (PTH)." (PMID 35626900, 2022). "Pseudohypoparathyroidism (PHP) consists of a heterogeneous group of disorders that exhibit one common feature, namely, resistance to the actions of the parathyroid hormone (PTH)." (PMID 35296306, 2022). "Pseudohypoparathyroidism (PHP) indicates a group of rare disorders characterized by end-organ resistance to various hormones, primarily parathyroid hormone (PTH)." (PMID 32481259, 2020). "However, PTH reveals an ability to auto-regulate, and a relative resistance to PTH may develop resulting in decreased calcium concentrations and increased phosphate concentrations (similarly to a PTH resistance in pseudohypoparathyroidism)." (PMID 29904370, 2018). "Pseudohypoparathyroidism (PHP) is a group of rare, related, highly heterogeneous disorders, which are characterized by end-organ resistance to parathyroid hormone (PTH) action." (PMID 29280743, 2017). "Pseudohypoparathyroidism (PHP) defines a group of rare heterogeneous metabolic disorders, characterized by resistance to the peripheral action of PTH, the most important hormone regulating the calcium and phosphorus homeostasis." (PMID 27871293, 2016). "Pseudohypoparathyroidism (PHP) includes a heterogeneous group of metabolic disorders characterized by hypocalcemia, hyperphosphatemia, and an elevated PTH level because of PTH resistance." (PMID 24651309, 2014). "The main clinical features of pseudohypoparathyroidism (PHP)/inactivating parathyroid hormone/parathyroid hormone-related protein signaling disorders (iPPSD), including parathyroid hormone (PTH) resistance, brachydactyly and short stature, develop during middle and late childhood." (PMID 39267114, 2024). "In pseudohypoparathyroidism lactotroph cells has shown a lack of responsivity to PTH, that normally increases plasma PRL in adults." (PMID 36967769, 2023). "Pseudohypoparathyroidism (PHP) constitutes a rare group of endocrine disorders, initially reported by Albright and colleagues in 1942, characterized by complete or partial failure of end-organ to respond to PTH." (PMID 37920253, 2023). "A moderate decrease in response potency to PTH(1‐34) but not PTHrP(1‐36) on the R186H mutant is consistent with the phenotype of pseudohypoparathyroidism without skeletal abnormalities seen in the patients with this mutation." (PMID 35720667, 2022). "Calcium and PTH level were found higher in the pseudohypoparathyroidism group whereas there was not any difference between two groups in terms of CaXP product and phosphorus level." (PMID 32267362, 2020). "Thus, in pseudohypoparathyroidism, defects in the GNAS gene interfere with PTH signaling in peripheral target tissues, particularly in the kidneys." (PMID 29694629, 2018).
pseudohypoparathyroidism (continued). "Pseudohypoparathyroidism type 1A (PHP1A/iPPSD2) is characterized by brachydactyly, short stature, round face, stocky appearance, ectopic calcifications (Albright hereditary osteodystrophy [AHO]), developmental delay, and resistance to PTH or other hormones binding G-protein coupled receptors (GPCR)." (PMID 39104441, 2024). "Methylation defects at GNAS exon A/B alone, or at several GNAS DMRs, are observed in pseudohypoparathyroidism type 1B (PHP1B), characterized by resistance to PTH and frequently TSH, but infrequently by AHO features." (PMID 32318528, 2020). "AHO in combination with PTH resistance and a diminished in vitro measured activity of Gsα protein characterizes pseudohypoparathyroidism type Ia (PHPIa, MIM: 103,580), the most common subtype of the rare group of disorders summarized under the term pseudohypoparathyroidism (PHP)." (PMID 25802881, 2015). "Pseudopseudohypoparathyroidism (PPHP) is defined as the presence of the AHO phenotype in the absence of PTH resistance." (PMID 33179219, 2021). "Patients with pseudopseudohypoparathyroidism (PPHP) exhibit most of the somatic features of AHO in the absence of PTH resistance." (PMID 25219572, 2015). "Patients with pseudopseudohypoparathyroidism (PPHP; OMIM #612463) have AHO but no resistance to PTH or other hormones." (PMID 24651309, 2014). "Pseudohypoparathyroidism type 1B/iPPSD3 (MIM#603233) patients classically show resistance to PTH and TSH in the absence of additional clinical features, but in the past years, patients showing physical features of AHO have been described." (PMID 30616679, 2019). "PHP1A is characterized by resistance to multiple hormones with features of Albright hereditary osteodystrophy (AHO), while pseudopseudohypoparathyroidism (PPHP) is characterized by AHO in the absence of PTH resistance." (PMID 31555217, 2019).
Hypomagnesemia (113 papers, 2002 to 2026). An abnormally decreased magnesium concentration in the blood. "For concomitant PPI use, deepening of hypokalemia is mediated through impaired parathyroid hormone secretion caused by hypomagnesemia resulting from long-term (over one year) PPI use." (PMID 37510753, 2023). "In conclusion, we found that hypomagnesemia was associated with higher serum calcium and PTH, and clinical symptoms were more common in patients with hypomagnesemia." (PMID 34416890, 2021). "Hyperglycemia causes osmotic diuresis accompanied by hypomagnesemia, which adversely affects parathyroid hormone (PTH) secretion." (PMID 34007765, 2021). "Magnesium is an important cation that binds to the CaSR, causing modest influence on PTH secretion, and hypomagnesemia can blunt effective PTH secretion." (PMID 33614549, 2021). "Hypomagnesemia is also associated with reduced release and activity of parathyroid hormone (PTH) and reduced synthesis of active vitamin D and its receptors." (PMID 32509580, 2020). "Severe hypomagnesemia (<0.4 mmol/L) causes reduced cAMP levels which can result in reduced secretion of PTH and increased peripheral resistance." (PMID 29849626, 2018). "Other authors report that hypomagnesemia involves intestinal loss, malabsorption, and abnormality of vitamin D and parathyroid hormone metabolism." (PMID 20953423, 2011). "The prognosis of hypomagnesemia depends on the underlying clinical condition, and the clinician’s experience in the differential diagnostic and therapy of electrolyte disorders and those associated with dysfunction of the parathyroid hormone axis." (PMID 40740723, 2025). "Cisplatin causes hypomagnesemia and hypocalcemia with excessive PTH, leading to bone resorption." (PMID 32575603, 2020). "CNI cause hypomagnesemia, leading to elevated levels of parathyroid hormone." (PMID 32575603, 2020). "In addition, molecular studies have suggested that severe hypomagnesemia causes blockage of PTH secretion by disinhibition of G[α] subunits and subsequently activation of the CaSR." (PMID 29849626, 2018). "While mild hypomagnesemia can stimulate PTH production, severe reductions in serum magnesium are known to suppress PTH." (PMID 40663633, 2026). "Hypomagnesemia impedes the Mg-dependent production of cAMP induced by adenyl cyclase, leading to the diminished release of PTH and subsequently lowering calcium levels, as PTH maintains calcium homeostasis." (PMID 40291321, 2025). "When hypomagnesemia occurs, cAMP production declines, leading to reduced parathyroid hormone (PTH) secretion and, consequently, lower blood calcium concentrations." (PMID 40282004, 2025). "Hypomagnesemia has been shown to suppress parathyroid hormone (PTH) secretion and induce resistance to PTH at target organs, thereby disrupting calcium and phosphate homeostasis." (PMID 40860924, 2025). "Serum analysis revealed hypomagnesemia (0.37 mmol/L) but normal Ca2+ (2.36 mmol/L) and PTH levels (3.8 pmol/L)." (PMID 39099563, 2024). "Hypomagnesemia results in decreased levels of parathyroid hormone and vitamin D3, which can affect calcium-phosphorus metabolism and impair bone resorption." (PMID 39758323, 2024). "Hypomagnesemia can hinder the release of PTH and potentially reduce the sensitivity of target organs to circulating PTH, leading to a biochemical pattern akin to primary hypoparathyroidism." (PMID 37446123, 2023). "Dogs with decreased 25(OH)D and SHPT were more likely to have ionized hypomagnesemia compared to dogs with decreased 25(OH)D and normal parathyroid hormone concentrations (P=0.015)." (PMID 36214464, 2022). "Hypomagnesemia significantly elevates the levels of alkaline P and PTH in patients with CKD stage 5 under maintenance HD." (PMID 35889897, 2022). "Hypomagnesemia also induces a reversible resistance to the actions of PTH at the level of both bone and kidney." (PMID 33247617, 2021).